ELP1 (elongator acetyltransferase complex subunit 1)
Diseases named in the same sentence as ELP1 in open-access papers (continued):
Sharing a sentence is not in itself a finding about the gene and the disease.
melanoma (4 papers, 2018 to 2024). A malignant, usually aggressive tumor composed of atypical, neoplastic melanocytes. "Mechanistically, Elp1 is activated by phosphorylation through an mTORC2-dependent pathway in melanoma cells." (PMID 39085648, 2024). "The enzymatic subunits of the elongator complex ELP1 and ELP3 and the thiolase CTU2 are overexpressed in human melanoma, particularly in melanomas carrying the BRAFV600E mutation." (PMID 33564819, 2021). "In a previous study the migration and tumorigenicity of melanoma-derived cells was shown to be significantly decreased upon depletion of ELP1, ELP3, ELP5 or ELP6 in melanoma cells." (PMID 30597914, 2018). "Since dynamic IKAP/Elp1 phosphorylation was also observed in human melanoma cells and change in response to insulin availability, pharmacological interference with this process may represent an attractive option to downregulate the Elongator function and possibly impair cancer cell proliferation." (PMID 30597914, 2018). "ELP1, ELP3, CTU1 and CTU2 are strongly upregulated in BRAFV600E cells and inactivation of ELP3 impaired the development of BRAFV600E melanoma in a zebrafish model." (PMID 30597914, 2018).
brain tumor (2 papers, 2018 to 2023). "In our cohort of pediatric brain tumor patients, we detected three variants in the ELP1 gene." (PMID 38139220, 2023).
Huntington disease (2 papers, 2019 to 2021). Huntington disease (HD) is a rare neurodegenerative disorder of the central nervous system characterized by unwanted choreatic movements, behavioral and psychiatric disturbances and dementia. "Our interested top ten common canonical pathways associated with Elp1 deficiency include Huntington’s disease signaling, acute phase response signaling, senescence pathway, and role of BRCA1 in DNA damage response." (PMID 34819065, 2021).
neuropathy (2 papers, 2014 to 2023). A disorder affecting the nervous system that manifests with pain, tingling, numbness, and/or muscle weakness. "Patient #7 with ELP1 variant had excessive toxicity to chemotherapy (severe vincristine neuropathy)." (PMID 38139220, 2023).
brain cancer (1 paper, 2023). A primary or metastatic malignant neoplasm affecting the brain. "Our data are a clear illustration that the mutational spectrum in a single gene such as ELP1 can lead to distinct and non-overlapping phenotypes ranging from peripheral neuropathy to complex multidimensional NDDs to predisposition to pediatric brain cancer." (PMID 36864284, 2023).
colorectal cancer (1 paper, 2023). A primary or metastatic malignant neoplasm that affects the colon or rectum. "Patients #6 and #7 with ELP1 variants both had grandparents with leukemia and colorectal cancer, respectively." (PMID 38139220, 2023).
Failure to thrive (1 paper, 2023). Failure to thrive (FTT) refers to a child whose physical growth is substantially below the norm. "Reduced growth has been described in this population, and the question remained whether this difference resulted from the medical fragility that this population endures throughout life, or if there was an inherent failure to thrive directly caused by the ELP1 mutation." (PMID 37943786, 2023).
glioblastoma (1 paper, 2026). The most malignant astrocytic tumor (WHO grade IV). "In this study, we evaluated the antiproliferative activity of the biopolymer p21-ELP1-Bac, a p21-derived peptide delivered via an elastin-like polypeptide (ELP1) carrier and a cell-penetrating peptide (CPP), across three glioblastoma cell lines: U87, GBM43, and GBM6." (PMID 41752375, 2026).
glioma (1 paper, 2023). A benign or malignant brain and spinal cord tumor that arises from glial cells (astrocytes, oligodendrocytes, ependymal cells). "However, the impact of the ELP1 variant on the appearance of high-grade glioma cases is not so straightforward due to cranial irradiation, a known risk factor for secondary tumors of this type." (PMID 38139220, 2023).
Gorlin syndrome (1 paper, 2023). "Given the population frequencies of 0.0962% for GPR161 and 0.0687% for ELP1, neither of these genes can be a cause of Gorlin syndrome with an unexplained population frequency far lower at 0.0021%." (PMID 36961676, 2023). "ELP1 and GPR161 therefore join PTCH2 as potential candidate genes for Gorlin syndrome that can be dismissed on their population frequencies and, for PTCH2 and GPR161, their absence in Gorlin syndrome kindreds." (PMID 36961676, 2023). "ELP1 and GPR161 can be dismissed as candidates for Gorlin syndrome and it now also seems unlikely that GPR161 homozygotes have Pituitary Stalk Interruption Syndrome." (PMID 36961676, 2023).
microcephaly (1 paper, 2021). A congenital or acquired developmental disorder in which the circumference of the head is smaller than normal for the person's age and sex. "Conditional deletion of the Elp1 subunit in mouse cortical progenitors leads to microcephaly by causing a reduction in IP rather than AP number, resulting in suppressed indirect neurogenesis." (PMID 33976153, 2021).
pilocytic astrocytoma (1 paper, 2023). Pilocytic astrocytoma is a rare subtype of low-grade glioma of the central nervous system characterized by a well circumscribed, often cystic, brain tumor with a discrete mural nodule and long, hair-like projections that extend from the neoplastic astrocytes. "Germline variants in the ELP1 gene have been associated with pilocytic astrocytoma for the first time." (PMID 38139220, 2023). "In patient #8 diagnosed with pilocytic astrocytoma and ELP1 germline variant, six relatives with unknown tumors in the father’s family were reported." (PMID 38139220, 2023).
ulcerative colitis (1 paper, 2022). An inflammatory bowel disease involving the mucosal surface of the large intestine and rectum. "In agreement with the notion that Elp3 deficiency is linked to an increased inflammatory status, patients suffering from ulcerative colitis showed lower levels of both Elp1 and Elp3." (PMID 35920020, 2022).
viral infection (1 paper, 2025). "Downstream U34 modification enzymes, ALKBH8 and CTU1, are essential for both SARS-CoV-2 and ZIKV replication—According to the U34 modification pathway, alteration of the two enzymatic steps downstream of the Elongator complex (ELP1-6) step to generate mcm5s2U would also affect viral infection." (PMID 40806605, 2025).
ZIKV infection (1 paper, 2025). "ZIKV infection levels, measured by the percentage of mCherry-positive cells, were significantly reduced in ELP1-KO cells compared to control cells at all MOIs tested (0.1, 2, and 5), ranging from approximately 42% to 47%." (PMID 40806605, 2025). "Using ELP1-KO cells, we confirmed that ELP1, and by extension, proper U34 tRNA modification, is essential for efficient ZIKV infection and viral protein synthesis." (PMID 40806605, 2025). "ELP1 knockout reduces both ZIKV infection rate and viral translation efficiency—To strengthen the tight relationship between U34 tRNA modifications and viral translation, we used a recombinant ZIKV expressing mCherry as a quantitative reporter of viral protein synthesis." (PMID 40806605, 2025).
cancer (10 papers, 2018 to 2024). A tumor composed of atypical neoplastic, often pleomorphic cells that invade other tissues. "Strikingly, around 95% (n = 301) of them were mapped to cancer pathways, evidencing a strong link between Elp1 deficiency and cancer." (PMID 34819065, 2021). "Overall, our findings indicate that cancer pathways are the most common feature associated with Elp1 deficiency." (PMID 34819065, 2021). "However, the pedigrees show that relatives of patients with ELP1-related MB have a low risk of developing cancer, which highlights that the penetrance is highly incomplete." (PMID 38962751, 2024). "Finally, by means of a mass spectrometry (MS)-based proteomics approach and bioinformatics tools, we show that differentially expressed proteins in Elp1-deficient MEFs were most significantly enriched in pathways related to cancer, apoptosis, and DNA repair." (PMID 34819065, 2021). "Apart from MB, no cancer was associated with ELP1 PVs; second tumors reported in 4 patients occurred within the irradiation fields, in the usual time-lapse for expected radiotherapy-induced neoplasms." (PMID 38962751, 2024). "Using a proteome-wide approach, we identified proteins that are biologically significant in the response to Elp1 knockout, and those proteins were enriched in several significant pathways such as cancer, apoptosis signaling, protein synthesis, and DNA damage response." (PMID 34819065, 2021). "Finally, using proteome analyses, we identified several proteins involved in cancer pathways and DNA damage responses as being differentially expressed upon Elp1 depletion." (PMID 34819065, 2021). "Our study reports no other cancer risk than MB risk associated with ELP1." (PMID 38962751, 2024). "We also performed disease and biological function analysis on these proteins, and found that important differentially-expressed proteins associated in common with Elp1 deficiency and/or IR treatment included non-hematological solid tumor, non-hematologic malignant neoplasm, cancer, and solid tumor." (PMID 34819065, 2021). "For six genes [ELP1, GPR161, VHL and SDHA/B/C], a clear lack of mutational constraint calls the pediatric penetrance and/or severity of associated cancers into question." (PMID 38424437, 2024). "In FD fibroblasts, EED226 did not change the H3K27me3/H3 ratio and the ELP1 exon 20 splicing pattern suggesting that this antitumor drug acts preferentially on cancer-derived cells while sparing primary cells." (PMID 38829854, 2024).
tumor (10 papers, 2009 to 2025). "Recently, germline loss-of-function IKBKAP/ELP1 variants were identified in patients with pediatric Sonic Hedgehog medulloblastomas, highlighting the role of Elongator and its subunits in tumor development." (PMID 34819065, 2021). "Altogether, our observations rather suggest a tumor spectrum restricted to childhood MB, and the tumor-free survival in ELP1-variant carriers indicates that the risk may be limited to the first 15 years of life." (PMID 38962751, 2024). "The delays between the second malignancy and irradiation, and the expected histology for a radiation-induced tumor with normal expression of ELP1 protein were rather compatible with a radiation-induced tumor." (PMID 38962751, 2024). "Fourteen percent of them have been reported with bi-allelic alterations of ELP1, a tumor-suppressor gene being currently the most frequent to predispose to MB." (PMID 35199222, 2022). "When the tumor volumes were calculated from these images, saline, saline+hyperthermia, and Bac-ELP1 treated tumors reached a total volume of 150 mm3." (PMID 23372821, 2013). "The cytotoxic activity of L12 can be modulated by conjugating this peptide to macromolecular carrier, ELP1, which preferentially aggregates and infiltrates tumor cells upon induction of hyperthermia, as has been shown in this study." (PMID 19513001, 2009). "A complete loss of cytoplasmic ELP1 staining in all tumor cells (with intra-tumoral vessels as a positive internal control) was observed in 12/57 (21%) of MB, SHH-activated, and was preserved in all other MB subgroups and in other tumor types." (PMID 35199222, 2022). "With tumors thus less exposed to doxorubicin delivered with an ELP2 rather than an ELP1, the less efficient tumor reduction seen with an ELP2 carrier is unsurprising." (PMID 35684309, 2022). "We have previously shown that the thermoresponsive ELP1 accumulates in the tumor much more rapidly than the non-thermoresponsive ELP2." (PMID 35684309, 2022). "However, the ELP1 construct also remains in the tumor for a prolonged period, while the ELP2 construct not only shows less initial accumulation, but also a much more rapid clearance from the tumor." (PMID 35684309, 2022).
neurodegenerative disease (9 papers, 2009 to 2023). A disorder of the central nervous system characterized by gradual and progressive loss of neural tissue and neurologic function. "We have provided evidence that the FD-associated ELP1 mutation promotes a dysfunctional gut-metabolism axis that in turn promotes pathology reminiscent of more common neurodegenerative diseases and other neurologic/neuropsychiatric conditions." (PMID 36639365, 2023).
neurologic disease (6 papers, 2012 to 2023). "The allele is highly penetrant and results in impaired splicing of ELP1 (formerly called IKBKAP 4,5), leading to a devastating neurologic disease first described in 19496 and now called Familial dysautonomia (FD)." (PMID 36639365, 2023).
peripheral neuropathy (4 papers, 2010 to 2023). A disorder affecting the peripheral nervous system. "Moreover, our data demonstrate that Acly’s activity regulates the mechanism underlying Tau mediated neurite morphology defects found in Elp1 KD suggesting the possible involvement of Tau dysfunction in the FD peripheral neuropathy." (PMID 36393857, 2022).
infection (3 papers, 2009 to 2025). The state of being infected such as from the introduction of a foreign agent such as serum, vaccine, antigenic substance or organism. "The substantial reduction in both infection levels and mCherry intensity underscores the importance of ELP1 for optimal ZIKV replication." (PMID 40806605, 2025). "To achieve higher infection levels than in primary fibroblasts (wt or FD), we used CRISPR/Cas9 to generate an ELP1 knockout (ELP1-KO) HeLa cell clone, which showed a near-complete loss of ELP1 protein compared to control HeLa cells." (PMID 40806605, 2025). "Consistent with the infection data, ZIKV viral translation, deduced from the mean mCherry intensity per infected cell, was also significantly reduced in ELP1-KO cells, with a decrease of approximately 39% to 47% across the same MOIs." (PMID 40806605, 2025).
neurodevelopmental disorder (3 papers, 2019 to 2025). A behavioral and cognitive disorder with onset during the developmental period that involves impaired or aberrant development of intellectual, motor, or social functions. "Five of these genes are already classified as diagnostic grade genes in the IEM panel (COQ4, ELAC2, MRPL44, MSTO1 and SKIV2L) and three others are diagnostic grade genes in different neurology and neurodevelopmental disorder gene panels (EIF2B4, ELP1, EXOSC8)." (PMID 36229886, 2022).
ELP1 also shares sentences with these, for which no sentence is quoted: autonomic neuropathies (4 papers); amyotrophic lateral sclerosis (3); genetic disorder (3); Rolandic epilepsy (3); epilepsy (2); meningococcal disease (2); adenocarcinoma (1); age-related macular degeneration (1); Ataxia (1); autism spectrum disorder (1); bacterial infections (1); bipolar disorder (1); breast carcinoma (1); cardiac failure (1); childhood cancer (1); cleft palate (1); CNS tumors (1); colon cancer (1); Dengue hemorrhagic fever (1); developmental delay (1); Down syndrome (1); Duchenne muscular dystrophy (1); glomerulonephritis (1); hematologic malignant neoplasm (1); hypotension (1); Immunodeficiency (1); keratoconus (1); leukemia (1); lung fibrosis (1); lupus (1).
A further 7 diseases each share a sentence with ELP1 in 1 paper.